CRP (C-reactive protein)
Diseases named in the same sentence as CRP in open-access papers (continued):
Sharing a sentence is not in itself a finding about the gene and the disease.
Sepsis (continued). "In this study, we assembled a cohort of patients with severe trauma and studied several common biomarkers, including PCT, CRP, IL-6 and SAA, with the overall goal of creating a panel that would allow discrimination of ICU patients who are at increased risk of sepsis." (PMID 38182736, 2024). "Similarly, one large multicentered American study of suspected sepsis in neonates found the initial CRP value to be poorly sensitive for SBI." (PMID 38254697, 2024). "Although CRP on its own possesses moderate diagnostic accuracy for differentiating between sepsis and non-sepsis, its efficacy is greatly improved when combined with PCT." (PMID 39201697, 2024). "The study found a substantial association between CRP and PCT in the context of sepsis." (PMID 38774176, 2024). "In addition to this, sepsis is impacted by various biomarkers and physiological parameters, such as C-reactive protein, white blood cell count, and central venous pressure." (PMID 39199728, 2024). "As CRP is known to induce NETosis, diminished CRP levels may be a mechanism counterbalancing increased NET formation in sepsis." (PMID 38099844, 2024). "CRP levels, however, were beginning to raise 2 days prior sepsis diagnosis (P = 0.009)." (PMID 39416748, 2024). "The early detection of sepsis in diabetic individuals with urinary tract infection may be achieved by using a combination of CRP, WBC, and ALB test findings." (PMID 38771840, 2024). "Considering the dynamic nature of BSI and sepsis and heterogeneity in individual CRP response trajectories, the centile reference charts developed here may provide a valuable tool for guiding individualised infection management." (PMID 38599549, 2024). "C-reactive protein (CRP) values were significantly higher in late-sepsis cases (p = 0.002)." (PMID 39457173, 2024). "However, there is currently insufficient evidence to monitor CRP to stop the antibiotic therapy in late-onset sepsis." (PMID 38535886, 2024). "The median CRP concentration in sepsis was 2.94-fold higher than in SIRS." (PMID 39434093, 2024). "Nevertheless, the testing results for ALB, WBC and CRP could be obtained within a shorter duration comparing to PCT, resulting into an earlier evaluation of sepsis risk in diabetic patients with UTI." (PMID 38771840, 2024). "While current biomarkers of sepsis have their limitations, such as the limited specificity of CRP and cytokines, assessment of a panel of these markers may still serve to support a diagnosis." (PMID 39716257, 2024). "Sepsis or septic shock was assessed based on the presence of these conditions, the use of vasopressors, or mean arterial pressure, while acute phase reactants were evaluated using C-reactive protein, fever, procalcitonin, or leukocyte count." (PMID 39334976, 2024). "Four studies combined the early sepsis marker IL-6 with CRP." (PMID 38671704, 2024). "Other common sepsis markers are CRP, procalcitonin, and interleukin-6 (IL-6)." (PMID 39091978, 2024). "Notably, AZU1 exhibited a higher AUC of 0.893, outperforming PCT and CRP with AUCs of 0.856 and 0.699, respectively, in differentiating sepsis from infections." (PMID 38357095, 2024). "Interestingly, the authors observed a positive linear correlation between serum sP2X7R and CRP, a serum marker of acute inflammation, in patients with acute inflammatory conditions such as infection/sepsis." (PMID 38069064, 2023). "The ADAPT-Sepsis trial aims to determine whether a treatment protocol based on monitoring CRP or PCT safely allows a reduction in duration of antibiotic therapy in adult patients with sepsis and to assess cost effectiveness." (PMID 37841304, 2023). "Meanwhile, our data revealed that body temperature (OR = 2.216, 95% CI 1.628 − 3.015, p < 0.001), body weight (OR = 0.518, 95% CI 0.397 − 0.677, p < 0.001) and CRP (OR = 1.072, 95% CI 1.046 − 1.099, p < 0.001) were independent indicators for the presence of sepsis." (PMID 36908271, 2023).
Sepsis (continued). "In addition, procalcitonin (PCT) and C-reactive protein (CRP) are known to be used to diagnose sepsis and predict its severity and mortality in patients." (PMID 38026334, 2023). "In this study, PSP was also superior to WBCs and CRP in predicting sepsis." (PMID 37894237, 2023). "PCT and CRP are among several biomarkers of inflammation and sepsis." (PMID 37760703, 2023). "Procalcitonin and CRP are used for the diagnosis of sepsis and in assessing the severity of sepsis." (PMID 37509420, 2023). "The pro-inflammatory biomarkers CRP and PCT are recommended and widely used as diagnostic tools and for monitoring infection and inflammation in patients with sepsis, especially when used in conjunction with clinical assessment and determination of other biomarkers." (PMID 37450054, 2023). "Finally, an interesting case report on primary empty sella syndrome misdiagnosed as recurrent sepsis included a CRP of 152 mg/L." (PMID 37873776, 2023). "Moreover, among these biomarkers, procalcitonin and CRP are significant factors for predicting the survival of AKI patients with sepsis-initiating CRRT." (PMID 36832265, 2023). "Significant results in univariate testing for the progression of disease according to the sepsis-1/2 definition were obtained for CRP, urea, potassium, SOFA, SAH, body temperature, Horovitz index, shock index, SAPS II, and vasopressor therapy with decreasing order of level of significance." (PMID 37628779, 2023). "Moreover, leucocytosis, higher C-reactive protein (CRP), and thrombocytopenia were reportedly significant sepsis markers, especially in LONS." (PMID 37629715, 2023). "Interestingly, data showed that the percentage of SLAMF7+ monocytes was strongly correlated with serum concentrations of C-reactive protein (CRP) (r = 0.38), which is a commonly used marker for inflammation and disease progress in sepsis." (PMID 36749634, 2023). "Therefore, CRP is commonly used as an important indicator, assisting in the diagnosis and treatment monitoring of sepsis." (PMID 38005386, 2023). "In this study, we aimed to determine whether leukocytecount, NLR, PLR, and CRP obtained from routine preoperative blood tests can be used topredict postoperative sepsis after PCNL in patients with renal stones." (PMID 37426769, 2023). "Along with the delayed presentation, the factors that contribute to the high rate of sepsis and mortality rates are increasing age, male gender, trauma, low hemoglobin, high serum CRP and total WBC count, hyponatremia, gangrene, and fascial necrosis in histopathological examination." (PMID 37213962, 2023). "Contrastingly, maternal risk factors in combination with increased CRP levels, which were previously employed for EOS screening in all newborns, have since fall 2021 been utilized exclusively for EOS screening in newborns displaying sepsis symptoms." (PMID 38255366, 2023). "PCRS: clinical sepsis event as the performance of a sepsis workup (white blood cell count, differential, CRP, blood and/or CSF, and urine cultures) along with antibiotics given for more than 48 h initiated within 72 h of CVCs removal as indicated by the medical team." (PMID 38259593, 2023). "However, at the Day5 and discharge time points, CRP levels were higher in SIRS compared with Sepsis patients and highest at the Discharge timepoint, although these were not statistically significant." (PMID 38332914, 2023). "In the present study, we evaluated the accuracy and usefulness of CPD, NE-SFL and NE-WY, as biomarkers for culture-proven bacteremia in hospitalized patients, in comparison with the other commercialized sepsis biomarkers in Japan, including CRP, PCT, presepsin, and IL-6." (PMID 37324133, 2023). "In addition to some common biomarkers for sepsis and inflammation, including C-reactive protein (CRP), procalcitonin, presepsin, interleukin (IL)-6, IL-8, and IL-10, α1-antitrypsin (AAT) and pentraxin 3 were examined in the current study." (PMID 37876022, 2023).
Sepsis (continued). "On the other hand, the ratio of neutrophils to lymphocytes reflects the diagnosis and prognosis of sepsis, and its evaluation is known to be superior to that of CRP and inferior to that of PCT; however, this ratio is also increased in coronary artery disease and cancer, limiting its use." (PMID 38137411, 2023). "However, the accuracy of sepsis prediction by CRP is limited by its low sensitivity, and the variation in reported cutoff values among studies greatly hinders the practical application of PCT in clinical settings." (PMID 37147598, 2023). "We could argue that, though serum concentration of CRP is in fact a late marker of infection, it still adds value to the calculation of neonatal sepsis prediction, especially when considered alongside other laboratory markers of infection." (PMID 36834338, 2023). "We identified four different trajectories of changes in CRP in patients with sepsis in the ICU." (PMID 37709919, 2023). "The low specificity of CRP to sepsis is its main drawback as a biomarker of sepsis in adults, which could explain why this biomarker is not used in veterinary medicine as a biomarker of sepsis to date." (PMID 37048125, 2023). "In the past few decades, a large number of serum (plasma) experimental tests have been conducted on sepsis patients, and the molecular markers of sepsis have been found to include C-reactive protein (CRP), procalcitonin (PCT), presepsin, interleukin-6 (IL-6), and neutrophil CD64." (PMID 36691469, 2023). "The independent association between a baseline procalcitonin > 4.24 ng/mL and the risk of in-hospital mortality in Cox regression analysis was maintained even after adjusting for C-reactive protein (mg/L) and sepsis status at admission (HR, 2.11; 95% CI, 1.20–3.70; P = 0.01)." (PMID 36647149, 2023). "Besides the standard sepsis biomarkers like C-reactive protein (CRP), procalcitonin (PCT), and lactate, most frequently used in diagnostics and monitoring, we also assess a new cytometric parameter Monocyte Distribution Width (MDW)." (PMID 36769843, 2023). "The use of CRP as the most important and critical immunochemical marker of several medical conditions, including infections such as sepsis, physiological organ diseases, various autoimmune disorders, malignancies and other health conditions, has become widely popular." (PMID 37873776, 2023). "The rise of the CRP concentration in sepsis is primarily induced by interleukin (IL)-6 and IL-1β." (PMID 37744876, 2023). "The independent association between a baseline procalcitonin level > 4.24 ng/mL and the risk of 50-day in-hospital mortality, in logistic regression analysis, was maintained even after adjusting for C-reactive protein (mg/L) and sepsis status at admission (OR, 2.63; 95% CI, 1.37–5.03; P = 0.004)." (PMID 36647149, 2023). "As seen in the ROC curve analysis, CRP levels were significant predictors of the development of sepsis, followed by the MHLA-DR expression rate and MFI of MHLA-DR, while the lymphocyte count (p = 0.286) and sepsis index (p = 0.05) were not significant predictors." (PMID 37509475, 2023). "However, CRP alone cannot distinguish sepsis from SIRS due to its elevated level in both conditions." (PMID 37714898, 2023). "It is important to note that IL-6 signalling did not account for all of the observed risk of sepsis with reduced small HDL particle count in either our observational analysis (adjusting for CRP) or our genetic analyses." (PMID 37814277, 2023). "Sepsis decreases lymphocyte counts and increases the CRP level." (PMID 37197571, 2023). "Notably, patients with sepsis who had intermediate CRP levels had the lowest in-hospital mortality rate." (PMID 37709919, 2023). "Other tests, such as procalcitonin (PCT) and C-reactive protein (CRP), are widely used as biomarkers of sepsis, but their specificity and sensitivity may vary depending on the type of infection and individual patient characteristics." (PMID 37510189, 2023).
Sepsis (continued). "IL-6 and CRP are often used in concert to aid in the diagnosis of sepsis." (PMID 37606448, 2023). "This study aimed to assess whether C-reactive protein (CRP), procalcitonin, and presepsin could be used to diagnose sepsis and predict mortality in patients with impaired renal function initiating CRRT." (PMID 36832265, 2023). "This suggests that one potential route by which IL6R blockade reduces the odds of severe sepsis is by reducing CRP, although this remains a hypothesis." (PMID 36716318, 2023). "This suggests that the observed links among the microbiota, CRP, and sepsis were unlikely to be confounded by the genetic predispositions that are typically represented by SNPs." (PMID 37662942, 2023). "And CRP mediate 31.53% effect of genus Gordonibacter on sepsis." (PMID 37662942, 2023). "In addition to the higher levels of CRP and haptoglobin observed, we found a very significant increase in IL-1Ra, IL-6, and IL-8 in the blood of all animals 24 h after sepsis onset." (PMID 38087374, 2023). "In patients with sepsis, the levels of CRP are typically elevated." (PMID 38005386, 2023). "Another study considered IL-1β inferior at predicting sepsis when compared to CRP, TNF and IL-6." (PMID 36769133, 2023). "Noteworthily, IL-6 1 week after sepsis onset, but not CRP, was also independently associated with mortality." (PMID 37241065, 2023). "Patient group 4 consisting of 184 term newborns (having considered maternal risk factors for sepsis but no clinical signs of sepsis) showed high CRP levels with a mean value of 27.8 mg/L, median 24.2 mg/L, min." (PMID 38255366, 2023). "Procalcitonin (PCT) and C-reactive protein (CRP) are commonly used biomarkers for sepsis." (PMID 38052864, 2023). "Several biomarkers, although nonspecific, could be used as surrogate markers of the proinflammatory and anti-inflammatory states of sepsis, such as CRP, TREM, TNF-α, IL-6, IL-10 and the TNF/IL-10 ratio." (PMID 37665397, 2023). "The possible variables of infection severity were comparable between mono- and polybacterial cases, including the rates of sepsis, organ failure, hypoxia severity, hyper- or hypothermia, acidosis, and elevation of inflammatory markers (CRP, leukocytosis) at the onset of VAP." (PMID 37370375, 2023). "CRP and procalcitonin were superior to presepsin for diagnosing sepsis." (PMID 36832265, 2023). "Regarding the prediction of sepsis severity, studies have indicated that elevated CRP and PCT levels were fair indicators of severity, being associated with fatal outcomes but not sufficiently accurate for the diagnosis of invasive bacterial infections in this specific population." (PMID 37892278, 2023). "Four variables (Alb, cd4_abs [pretransplant CD4 count], elevated CRP and sepsis) were selected." (PMID 37155023, 2023). "CRP is a common sepsis biomarker released in response to infection or cytokine stimulation." (PMID 37376129, 2023). "Diagnostic performance was evaluated and showed better performance for DLL1 for the recognition of sepsis (AUC: 0.823; CI 0.731–0.914) than C-reactive protein (AUC 0.758; CI 0.658–0.857), PCT (AUC 0.593; CI 0.474–0.711) and White Blood Cell count (AUC 0.577; CI 0.46–0.694)." (PMID 37298115, 2023). "ICU patients with SARS-CoV-2 infection (Cohort A), grouped into increasing and decreasing RNase 1 serum levels, were evaluated for various biomarkers and scores (lactate, IL-6, PCT, CRP, sepsis-related organ failure assessment (SOFA) score, and Horowitz score) over a 14-day period." (PMID 37569802, 2023). "Therefore, using the threshold values of 15 mg/L for CRP and 2 ng/L for procalcitonin value is acceptable to differentiate clinical and suspected sepsis at the postnatal 24th hour in our study." (PMID 37684308, 2023). "Therefore, it is clinically important to examine the CRP trajectories of patients with sepsis in real-world ICU settings." (PMID 37709919, 2023).
Sepsis (continued). "After 3, 7, and 10 days of treatment, there were significant differences in sepsis score and highly sensitive (hs)-CRP between groups I and II (p values for sepsis score were 0.009, 0.006, and 0.004, respectively, and for hs-CRP they were 0.015, 0.001, and 0.001, respectively)." (PMID 36769240, 2023). "In the literature, increased levels of sTREM-1 in septic patients have been reported, indicating that it is a reliable biomarker, the levels of which could predict survival rates in sepsis better than PCT or CRP." (PMID 37686271, 2023). "This study aimed to assess whether CRP, procalcitonin, and presepsin could be used to diagnose sepsis and predict mortality in patients with impaired renal function undergoing CRRT." (PMID 36832265, 2023). "The objective of this systematic review was to determine whether PCT, CRP, IL-6, and sCD14 are independent prognostic factors for predicting mortality in critically ill adults with sepsis." (PMID 37537680, 2023). "Importantly, our findings suggest that C-reactive protein (CRP) acts as a mediator of the impact of the gut microbiota on sepsis." (PMID 37662942, 2023). "In conclusion, C-reactive protein was the most sensitive marker for hand osteomyelitis, but was not universally elevated, and CRP >100 mg/L was associated with sepsis." (PMID 35130740, 2023). "In a prospective multicenter study, plasma from 21 infants with clinical sepsis was analyzed for biomarkers, including IL-1Ra, IL-6, circulating intercellular adhesion molecule-1 (clCAM-1) and CRP, in a ten-day period over a septic episode and compared to 20 infants with no infection." (PMID 36769133, 2023). "Fourthly, through the use of PhenomeScan, we found that no SNPs from the microbiota, CRP and sepsis were associated with infections, malignant diseases, or antibiotic use." (PMID 37662942, 2023). "The aetiology of a high CRP can be evaluated as septicaemia." (PMID 37308964, 2023). "We did not observe any significant correlation for PBMC or plasma miR-93-5p levels with the Sepsis-related Organ Failure Assessment (SOFA) score, C-reactive protein (CRP) levels, the Mortality in Emergency Department Sepsis (MEDS) score, or the Charlson Comorbidity Index (CCI)." (PMID 37261908, 2023). "Based on the results of this systematic review and meta-analysis, it can be concluded that six factors are consistently and significantly associated with ARDS in patients with sepsis: SOFA score, APACHE II score, pulmonary sepsis, smoking, pancreatitis, and CRP." (PMID 37143620, 2023). "Relevant clinical data, including age, duration of hospital stay, wound status, Fournier's gangrene severity index (FGSI) scores, sepsis markers (C-reactive protein (CRP), neutrophil-to-lymphocyte ratio, and procalcitonin), and pain assessment, were recorded and compared between the two groups." (PMID 38058329, 2023). "The specificity and accuracy of procalcitonin and CRP in sepsis have been compared." (PMID 36800584, 2023). "We can hypothesize that after the early phase of sepsis, where inflammatory markers such as IL-8, IL-6, CRP, or procalcitonin are highly elevated, ATP is also released as a danger signal." (PMID 38094297, 2023). "The CAR has recently been recognized as more useful than CRP or albumin alone for sepsis." (PMID 37576105, 2023). "CRP is one of the biomarkers used for sepsis diagnosis and follow-up." (PMID 37970921, 2023). "Regarding SAA and CRP, serum amyloid A is superior to CRP as a marker of early-onset sepsis." (PMID 37374228, 2023). "The dynamics of CRP, sepsis index, and MHLA-DR expression over time differed between groups." (PMID 37509475, 2023). "When comparing clinical and laboratory data, we found a higher frequency of fever (61.1% vs. 42.6%; p < 0.001) and sepsis (3,4% vs. 0.7%; p = 0.037) and higher levels of C-reactive protein (14.6 mg/L vs. 6.9 mg/L; p < 0.001) in patients with viral coinfections." (PMID 37845714, 2023).